TRIB2 (tribbles pseudokinase 2)
Description:
Interacts with MAPK kinases and regulates activation of MAP kinases. Does not display kinase activity (By similarity).
Synonyms: TRB2; GS3955; C5FW
Tractability: PROTAC: ubiquitination databases record sites on it; a small molecule that binds it is known.
Gene: Protein-coding gene on chromosome 2 (12,716,910 to 12,742,734, forward strand). Ensembl gene ENSG00000071575.
Subcellular location: Cytoplasm; Cytoplasm, cytoskeleton
Subcellular location (Human Protein Atlas): Nucleoplasm; Cytosol
Gene Ontology:
Molecular function: protein binding; mitogen-activated protein kinase kinase binding; nucleotide binding; protein kinase activity; RNA polymerase II-specific DNA-binding transcription factor binding; ubiquitin protein ligase binding; ubiquitin-protein transferase regulator activity
Biological process: negative regulation of interleukin-10 production; negative regulation of fat cell differentiation; positive regulation of proteasomal ubiquitin-dependent protein catabolic process; protein phosphorylation; regulation of MAP kinase activity
Cellular component: cytoplasm; nucleus; cytoskeleton
Genetic constraint (gnomAD): Loss-of-function variants: 2 observed, 28.29 expected, observed/expected ratio (o/e) 0.0707, 90% interval 0.028 to 0.22. The upper end of that interval is the gene's LOEUF score, 0.22, which puts it in group 1 of 6, group 1 being the genes least tolerant of losing a copy. Missense variants: 306 observed, 471.39 expected, observed/expected ratio (o/e) 0.65, 90% interval 0.59 to 0.71. Synonymous variants: 189 observed, 200.19 expected, observed/expected ratio (o/e) 0.94, 90% interval 0.84 to 1.07.
Homologues: Orthologues: chimpanzee TRIB2 (99% identical), dog TRIB2 (99% identical), macaque TRIB2 (99% identical), pig TRIB2 (99% identical), rabbit TRIB2 (99% identical), guinea pig TRIB2 (98% identical), mouse Trib2 (98% identical), rat Trib2 (98% identical), tropical clawed frog trib2 (72% identical), zebrafish trib2 (47% identical), Drosophila melanogaster trbl (37% identical). Paralogues in human: TRIB1 (59% identical), TRIB3 (44% identical), STK40 (26% identical).
Diseases named in the same sentence as TRIB2 in open-access papers:
TRIB2 is named in the same sentence as 77 diseases in open-access papers, as found by Europe PMC text mining. Sharing a sentence is not in itself a finding about the gene and the disease. The quoted sentences say what the papers report.
acute myeloid leukemia (23 papers, 2012 to 2026). Acute myeloid leukemia (AML) is a group of neoplasms arising from precursor cells committed to the myeloid cell-line differentiation. "In hematological malignancies, TRIB2 has been implicated in acute myeloid leukemia (AML), as well as T-cell acute lymphoblastic leukemia (T-ALL)." (PMID 27462446, 2016). "TRIB2 has also been associated with hematologic abnormalities including acute myelogenous leukemia." (PMID 22589742, 2012). "TRIB2 is a potential novel therapeutic target both for acute myeloid leukemia (AML) and acute lymphoblastic leukemia (ALL)." (PMID 31337155, 2019). "TRIB2 is overexpressed in human acute myeloid leukemia (AML) and accelerates AML progression via the inactivity of C/EBPα." (PMID 30541550, 2018). "Especially, Trib2 functions as an oncogene, and ectopic expression of Trib2 induces acute myelogenous leukemia following transduction into hematopoietic progenitor cells." (PMID 27550848, 2016). "Trib2-reconstituted mice uniformly developed fatal transplantable acute myelogenous leukemia." (PMID 35790734, 2022). "Furthermore, TRIB2 binds to and facilitates the degradation of CCAAT/enhancer-binding protein alpha (C/EBP-α) in a process proposed to be a key feature of TRIB2-induced acute myelogenous leukemia." (PMID 33546420, 2021). "In addition, RFWD2 accelerates the development of Trib1- and Trib2-induced acute myeloid leukemia in mouse models, which is abrogated when Rfwd2 or Trib1/2 is deleted or mutated." (PMID 34646775, 2021). "It has been observed that TRIB2 is highly expressed in several acute myeloid leukemias lacking C/EBP-α mutations." (PMID 24137458, 2013). "Trib2 gene is first identified as a myeloid oncogene, which contributes to acute myeloid leukemia (AML) in a bone marrow transplant model." (PMID 35790734, 2022). "TRIB2-mediated degradation of C/EBPα was found to have an oncogenic role in the development of acute myeloid leukemia (AML), and in lung and liver models of cancer, whereas TRIB2-mediated degradation of C/EBPβ has been found to suppress adipogenesis in vitro." (PMID 27563873, 2016). "A study demonstrated that rats treated with the TRIB2 gene contracted acute myeloid leukemia (AML) and the TRIB2 gene appears to be underexpressed when the growth of leukemia cells is inhibited." (PMID 24137458, 2013). "Strong evidence demonstrated that dysregulated TRIB2 expression contributed to the pathogenesis of acute myeloid leukemia (AML)." (PMID 23071539, 2012). "TRIB2 may serve as an adaptor of the E3 ligase COP1 and inactivate C/EBPα in acute myelogenous leukemia." (PMID 34586732, 2021). "Recent work demonstrated that afatinib, an approved irreversible electrophilic covalent EGFR/HER2 inhibitor for lung cancer treatment, increased TRIB2 degradation in human acute myeloid leukemia (AML) cancer cells, demonstrating for the first time that TRIB2 might be a druggable protein." (PMID 34198908, 2021). "In hematological malignancies, TRIB2 as a target gene of MEIS1, E2F1, and NOTCH1 participates in acute myeloid leukemia (AML) and T cell acute lymphoblastic leukemia (T-ALL)." (PMID 33794905, 2021). "TRIB2 has previously been identified as an oncogene that causes acute myelogenous leukemia via inactivation of the transcription factor, CEBPA (CCAAT/enhancer-binding protein alpha); however, to date there is no established relationship of TRIB2 with chemo-resistance." (PMID 29312632, 2017).
melanoma (22 papers, 2011 to 2024). A malignant, usually aggressive tumor composed of atypical, neoplastic melanocytes. "Trib2, circRNA-0084043, and miR-429 are the leading causes of migration and invasion in human melanoma tissues and cell lines." (PMID 33794905, 2021). "Further, evaluation of TRIB2 in these melanoma cell lines confirmed its expression promotes cell survival in a similar fashion." (PMID 38672402, 2024). "High circ_0084043 and TRIB2 expression, with low miR-429 expression, in malignant melanoma, elucidates interactive regulatory connections between these three RNA molecules." (PMID 38672402, 2024). "Silencing TRIB2 has been observed to reduce cell proliferation, colony formation, and wound healing in melanoma cells." (PMID 38794149, 2024). "A similar effect was previously observed in melanoma tumor tissues where high TRIB2 expression correlated with increased Akt phosphorylation." (PMID 37528172, 2023). "Recent studies support a role for TRIB2 as an emerging novel biomarker of chemoresistance in leukemia, melanoma, osteosarcoma, glioblastoma, and lung and ovarian cancers." (PMID 38254916, 2023). "The aggressive nature of prostate cancer cells post-enzalutamide therapy, correlates well with aggressive melanoma and lung cancer cells which overexpress TRIB2." (PMID 34973338, 2022). "The characteristics of TRIB2 structure and signal transduction and its role in many cancer subtypes focus on the function of TRIB2 in the therapeutic resistance of melanoma, leukemia, and glioblastoma." (PMID 36035171, 2022). "High TRIB2 expression was shown to be essential in melanoma progression, lung tumorigenesis, liver and colon tumors." (PMID 33794905, 2021). "In particular, knockdown of NOVA1 and TRIB2 has been shown to inhibit melanoma cell proliferation, migration, and invasion partly through promoting nuclear translocation of FoxO3a." (PMID 34418600, 2021). "A multifunctional role of TRIB2 as an oncogenic protein has been described in numerous cancers where it is overexpressed, including melanoma, leukemias, pancreatic cancer, liver cancer, epithelial ovarian cancer and lung cancer." (PMID 34070799, 2021). "In malignant melanomas, Trib2 is overexpressed and inhibited FOXO (forkhead box protein O) tumor suppressor activity." (PMID 33794905, 2021). "In vitro studies demonstrated that NOVA1 and TRIB2 transcript levels were up-regulated in melanoma malignancies and melanoma cell lines." (PMID 34418600, 2021). "Melanoma is the tissue with the highest expression of TRIB2 and its expression level correlates with each melanoma stage." (PMID 34070799, 2021). "Expression of TRIB2 is increased in melanoma, colon and pancreatic cancer which leads to impaired therapeutic response and poor clinical outcome." (PMID 34282050, 2021). "TRIB2 exhibits low expression in healthy skin samples, increases in benign melanoma, with the highest expression seen in malignant melanoma samples." (PMID 34070799, 2021). "Here, we review the characteristic features of TRIB2 structure and signalling and its role in many cancer subtypes with an emphasis on TRIB2 function in therapy resistance in melanoma, leukemia and glioblastoma." (PMID 34070799, 2021). "We have previously characterized a novel molecular mechanism of therapy resistance in melanoma mediated by the kinase-like protein Tribbles homologue 2 (TRIB2)." (PMID 33316942, 2020). "We first extracted data from the GEO profiles and screened a panel of cell lines for TRIB2 mRNA levels and identified human malignant melanoma cells UACC-62 as the cell line with the highest level of endogenous of TRIB2." (PMID 33316942, 2020).
melanoma (continued). "The expression level of TRIB2 considerably varies among cell and tumor types, with melanoma and glioblastoma being the cancers that most strongly express TRIB2." (PMID 33316942, 2020). "TRIB2 is involved in the etiology of various cancers, including leukemia, melanoma, lung cancer, and HCC." (PMID 32554864, 2020). "TRIB2 expression has been reported as a biomarker for diagnosis and progression of cancers including melanoma." (PMID 29599919, 2018). "TRIB2 is involved in the aetiology of a number of cancers including acute leukaemia, melanoma, ovarian, lung and liver cancer." (PMID 29599919, 2018). "In humans, Trib2 has been identified as a repressor of FoxO in malignant melanomas and complimentarily, FoxO represses Trib3 expression to derepress Akt and enhance insulin sensitivity in hepatocytes." (PMID 25329475, 2014). "Trib2 has been shown to be a repressor of FOXO in malignant melanoma, and Trib3 expression is altered in colorectal cancer." (PMID 21811619, 2011). "In an in vivo melanoma xenograft model, TRIB2 knockdown significantly reduced tumor growth." (PMID 38794149, 2024). "Especially, TRIB2 could be used to indicate progression and the response to chemotherapy in ex vivo clinical samples of melanoma." (PMID 35751033, 2022). "Thus, Trib2 is important in cell proliferation, colony formation, maintenance, and progression of melanoma cells." (PMID 33794905, 2021). "Moreover, TRIB2 levels appear to correlate with many neoplasia conditions, conferring TRIB2 a role as a biomarker, which in contexts such as melanoma is even dependent on cancer stage progression and prognosis." (PMID 34070799, 2021). "Given the correlation between TRIB2 expression levels and the stage of melanoma, TRIB2 could be used as a biomarker for diagnosis and progression." (PMID 34070799, 2021). "The oncogenic activity of TRIB2 is linked to its dysregulated expression, rather than to mutational activation, as in the case of melanoma and colorectal cancer, where TRIB2 is overexpressed and inversely correlated with survival of patients." (PMID 34070799, 2021). "In vivo, TRIB2 knockdown in melanoma xenograft models shows significant reduction of tumour growth." (PMID 34070799, 2021). "It is known that Trib2 has diverse roles in neurological disorders, metabolic diseases, autoimmune and inflammatory diseases, arthritis, and a number of cancers (chronic myeloid leukemia, liver, melanoma, and ovarian)." (PMID 33794905, 2021). "Also, NOVA1 (RNA-binding proteins) and tribbles pseudokinase 2 (TRIB2) (mammalian homolog of the Drosophila gene tribbles) have been shown to contributes to the maintenance of the malignant phenotype of melanoma cells through inhibition of FoxO3a activity." (PMID 34418600, 2021). "Furthermore, our studies identified TRIB2 as a novel oncogene and as a biomarker in melanoma, whose expression correlates with disease stage." (PMID 33316942, 2020). "Indeed, TRIB2 has been identified as a candidate biomarker for melanoma diagnosis and progression, because it exhibits low expression in healthy skin samples, increases in benign melanoma, with the highest expression seen in malignant melanoma samples." (PMID 27908682, 2017). "Moreover, knockdown of circ_0084043 or TRIB2 suppressed melanoma development, indicating that they could be a potential therapeutic target." (PMID 34070799, 2021). "In line with this, TRIB2 could be used as a biomarker in melanoma since its expression strongly correlates specifically with both the presence and progression of melanocyte-derived malignancies but not in samples from other tumour sources, including non-basal skin carcinoma." (PMID 34070799, 2021). "For instance, TRIB2 promoted AKT activation and, consequently, the inactivation of the transcription factor FOXO in melanoma." (PMID 34198908, 2021). "Moreover, TRIB2 has been identified as a repressor of FOXO proteins contributing to the growth and survival of melanoma cells." (PMID 34070799, 2021).
melanoma (continued). "However, the biological role of TRIB2 in CRC has not been elucidated, while TRIB2-mediated effects in leukemia, melanoma and liver cancer have been characterized more thoroughly." (PMID 34070799, 2021).
lung carcinoma (19 papers, 2012 to 2023). "Here, we further found that a high TRIB2 level is associated with the poor survival of patients with lung cancer and promotes lung cancer proliferation by regulating aerobic glycolysiss via PKM2-related factors." (PMID 35790734, 2022). "We previously reported that TRIB2 promotes lung cancer development and may play an oncogenic role in lung cancers associated with poor outcomes." (PMID 34646775, 2021). "For example, TRIB2 overexpression has been found in human lung cancers and in non-small lung cancer cells that express low levels of C/EBPα." (PMID 38254916, 2023). "As a result, LDHA and GLUT1 promote the aerobic glycolysis to provide energy for TRIB2-treated lung cancer cells." (PMID 35790734, 2022). "The affinity purification and mass spectrometry were further employed to examine the TRIB2 interactome and investigate the mechanism of TRIB2 in lung cancer." (PMID 35790734, 2022). "Via reduced phospho-Smad3/Smad3, miR-206 and miR-140 downregulate TRIB2 to further suppress lung cancer cell proliferation and metastasis." (PMID 35790734, 2022). "In the present work, the affinity purification and mass spectrometry were employed to analyze the TRIB2 interactome in vitro to further investigate the detailed mechanism of TRIB2 and its interacting with protein in lung cancer." (PMID 35790734, 2022). "Here, TRIB2 expression increased in lung cancer, and GST-TRIB2-full were then constructed and incubated with the lysis of lung cancer tissues." (PMID 35790734, 2022). "The results showed that PKM2 or TRIB2 suppression significantly inhibited lung cancer cell proliferation and migration compared with those in controls." (PMID 35790734, 2022). "The oncogenic roles of TRIB2 have also been described in other cancers where it is overexpressed, such as lung cancer, liver cancer, melanoma, and pancreatic cancer." (PMID 35790734, 2022). "TRIB2 has been shown to contribute to tumorigenesis in lung cancer through the downregulation of C/EBPα and TRIB2 direct interaction with AKT has been shown to be an important mechanism that contributes to resistance to anti-cancer drug therapy." (PMID 34944947, 2021). "Next, we collected seven lung cancer and adjacent normal lung-tissue samples for Western blotting to detect the expression of TRIB2." (PMID 34646775, 2021). "In lung cancer, TRIB2 blocks C/EBP-α activity by direct binding promoting the ubiquitination of C/EBP-α and consequently its proteasomal degradation through the interaction between the E3 ligase TRIM21 and the C-tail of TRIB2." (PMID 34070799, 2021). "To further determine the mechanism of TRIB2 in the progression and development of lung adenocarcinoma (LUAD), we detected the expression of TRIB2 in lung cancer and adjacent normal lung tissues by immunohistochemistry analysis." (PMID 34646775, 2021). "Previously, we observed that TRIB2 promoted the proliferation and migration of lung cancer cells in vitro and in vivo." (PMID 34646775, 2021). "Elevated Trib2 expression has oncogenic properties in both leukaemia and lung cancer dependent on interactions with proteasome machinery proteins and degradation of transcription factors." (PMID 29670085, 2018). "Overexpression of TRIB2 led to tumorigenesis of lung cancer, while downregulation of TRIB2 inhibited cell proliferation in cervical carcinoma and lung cancer cells." (PMID 29312632, 2017). "Overexpression of TRIB2 leads to tumorigenesis of lung cancer, while downregulation of TRIB2 inhibits cell proliferation in cervical carcinoma and lung cancer cells." (PMID 29312632, 2017). "Overexpression of TRIB2, resulting from gene amplification, has been described in lung cancer with a potential role in tumorigenesis." (PMID 27481518, 2016). "TRIB2 has previously been shown to function as an adaptor mediating the degradation of C/EBPα via COP1 E3 ligase in AML or TRIM21 E3 ligase in lung cancer, and these are likely candidates that link the TRIB2 pseudokinase domain to ubiquitination." (PMID 27563873, 2016).